BMPR1A (bone morphogenetic protein receptor type 1A)
Diseases named in the same sentence as BMPR1A in open-access papers (continued):
Sharing a sentence is not in itself a finding about the gene and the disease.
soft tissue sarcoma (1 paper, 2016). A malignant neoplasm arising from muscle tissue, adipose tissue, blood vessels, fibrous tissue, or other supportive tissues excluding the bones. "Metalloproteinase expression has previously been linked to prognosis in soft tissue sarcomas, and BMPR1A is necessary for extracellular matrix deposition by osteoblasts." (PMID 27114889, 2016). "This study suggests that BMPR1A-biased BMP2 signalling leads to disease progression in soft tissue sarcomas and that this outcome is linked to ECM remodelling." (PMID 27114889, 2016). "Specifically, we investigated the role of high BMPR1A expression within the context of high BMP2 expression in soft tissue sarcomas and found a significant association with reduced disease free survival." (PMID 27114889, 2016). "Thus, in addition to ECM remodelling and reduced bone formation, soft tissue sarcoma patients with BMPR1A-biased BMP2 expression are more likely to show tumour progression in the presence of high levels of endogenous BMP2." (PMID 27114889, 2016).
thyroid (1 paper, 2021). "Literature regarding the role of BMPR1A in thyroid carcinogenesis are still scanty." (PMID 33821390, 2021).
tumor (57 papers, 2004 to 2025). "TGF-beta pathway dysregulation is frequently observed in CRC, particularly through mutations in SMAD4 and BMPR1A, which have been associated with tumor aggressiveness and poor prognosis." (PMID 40282501, 2025). "Our findings from genetic analyses of constitutional and tumor tissues and histological evaluation of tumor tissues highlight the complex genotype-phenotype relationships of BMPR1A variants." (PMID 41023686, 2025). "Another possible explanation was that the test detected a somatically acquired BMPR1A variant from circulating tumor cells." (PMID 41250769, 2025). "The H/L patients exhibited higher frequencies of NF1, CBL, MAPK3, and BMPR1A mutations, underscoring the need for further research into their functional roles in tumor progression." (PMID 40282501, 2025). "In 50–60% of JPs patients’ genomes, a germline mutation is found in SMAD4 or BMPR1A tumor suppressor genes involved in the BMP/TGF-β signaling pathway." (PMID 36553592, 2022). "We observed that CD11b+/Ly6C+ cells in tumor naïve bone marrow and spleen tissues decreased upon loss of BMPR1a signaling, confirming the supporting role of BMPs in maintaining myeloid progenitor cell populations." (PMID 32318332, 2020). "We profiled myeloid subsets in the bone marrow, spleen and primary tumor and found myeloid BMPR1a loss altered the differentiation and lineage capability of distinct populations by histologic, flow cytometry and high dimensional mass cytometry analysis." (PMID 32318332, 2020). "In the case of PMS2 and BMPR1A variants, the former appears to be penetrant on the basis of tumor studies, whereas the significance of the latter is unclear." (PMID 29909963, 2018). "Our results indicate that when cancer is already formed and driven by a powerful oncogene that is capable of metastasis, the loss of BMPR1a reduces tumor burden and metastatic potential." (PMID 26274893, 2015). "When BMPR1a was first identified as the gene responsible for the formation of polyps in JPS patients, it was quickly labeled a tumor suppressor, because loss of normal functioning BMPR1a results in polyp formation." (PMID 26274893, 2015). "Possible explanations for different phenotypes associated with constitutionally mutant BMPR1A alleles include at least location and type of constitutional variant, somatic changes in tumor tissues, possible modifying constitutional variants, and environmental influences." (PMID 41023686, 2025). "This tumor cell migration ends with loss of BMPR1a expression." (PMID 26274893, 2015). "In four patients, longitudinal analysis of subsequent lesions highlighted an increase in mutations, like missense or splice variants in the PMS2, SMARCA4, ARID1A, AKT1, BMPR1A, and PTEN genes, suggesting tumor evolution." (PMID 41514647, 2025). "In FCCX-W, the predisposing BMPR1A variant was a missense change, and we utilized exome sequencing data for LOH analysis by comparing the reference to mutant allele ratios in tumor and normal DNA." (PMID 41023686, 2025). "In four patients, longitudinal analyses of subsequent lesions showed the maintenance of most genomic alterations and enrichment in missense or splice variants in PMS2, SMARCA4, ARID1A, AKT1, BMPR1A, and PTEN, indicating the occurrence of tumor evolution." (PMID 41514647, 2025). "Inactivation of Bmpr1a in T cells resulted in impaired generation of Treg, leading to the reduced tumor growth in mice bearing B16 melanoma cells." (PMID 35693928, 2022). "Our previous findings that BMPR1a deletion in the myeloid LysMCre mouse model restricted primary prostate growth furthers the tumor promoting capacity that BMPs provide." (PMID 34956082, 2021). "Tumors were also stained for BMPR1a and pSMAD1/5/8 by IHC to determine if myeloid BMPR1a deletion impacts BMPR1a expression and signaling in the tumor microenvironment." (PMID 32318332, 2020). "Conditional knockout of BMPR1a in a mammary tumor mouse model delayed tumor initiation and prolonged survival." (PMID 32318332, 2020).
tumor (continued). "CyTOF analysis of the tumor, bone marrow, and spleen of control and BMPR1a knockout mice was performed to identify changes in immune cell population clusters." (PMID 32318332, 2020). "Flow analysis for immune cells in the spleen of tumor bearing mice exhibited no change in CD11b+ myeloid, CD11b+/Ly6C+ monocyte and CD11b+/Ly6G+ neutrophil populations, but showed a significant increase in F4/80+ macrophages in the BMPR1a cKO tumor mice." (PMID 32318332, 2020). "Analysis of tumor pathology revealed subtle changes in morphology of the tumors from the CTL mice compared to the BMPR1A cKO." (PMID 32318332, 2020). "Similar data were obtained when tumor organoids expressing shRNA targeting Bmpr1a, marked by mCherry expression, were mixed and transplanted together with control organoids, marked by EGFP, into the same in vivo microenvironment." (PMID 31036156, 2019). "(F) Tumor organoids were infected using a lentivirus containing control shRNA with EGFP or shRNA targeting Shh or Bmpr1a with mCherry." (PMID 31036156, 2019). "(D, E) Gene set enrichment analysis (GSEA) of tumor allografts expressing control shRNA and shRNA targeting Shh (D), or shRNA targeting Bmpr1a (E) from RNA-Seq data using standard luminal signatures obtained from previous study." (PMID 31036156, 2019). "(H) Expression of SHH or BMPR1A in tumor xenografts from mice injected with J82 carrying shRNA targeting SHH or BMPR1A, respectively." (PMID 31036156, 2019). "Their RNASeq data indicated that MSI‐2 acts as a pleiotropic inhibitor of known intestinal tumor suppressors, including Lrig1, Bmpr1a, Cdkn1a, and Pten." (PMID 26775684, 2016). "To further explore the consequences of BMPR1a conditional deletion, we chose to measure the ability of the primary tumor cells to migrate and invade." (PMID 26274893, 2015). "Several putative or known tumour-suppressor genes have been mapped to 10q, including BMPR1A on 10q23.2 and PTEN/MMAC1/TEP1 on 10q23.3." (PMID 15026806, 2004). "Recent studies have highlighted the regulatory role of miRNAs on BMPR1A in tumor progression." (PMID 38783645, 2024). "BMPR1A is considered to be a promoter of tumor metastasis in various cancer types." (PMID 38783645, 2024). "In authentic NPC tumours, expression of BMPR1A was increased relative to normal nasal epithelium." (PMID 32708289, 2020). "Along with our data, all of these findings suggest that reduced expression of BMPR1B and BMPR2, and/or increased expression of BMPR1A, may play a role in the determination of a proliferative cell fate, at least in some types of tumours." (PMID 32714600, 2020). "Furthermore, we genetically ablated Bmpr1a from BBN-induced tumor organoids derived from Bmpr1aflox/flox mice by expressing Cre recombinase." (PMID 31036156, 2019). "In conclusion, the data indicate that BMP signaling through BMPR1a functions as a tumor promoter." (PMID 26274893, 2015). "We speculate that the various effects of BMPs on proliferation, differentiation, and apoptosis of tumor cells may be related to the expression levels of BMPR1A." (PMID 23531103, 2013). "Several studies have shown that BMPR1A plays a role in suppression of tumor progression." (PMID 23531103, 2013). "BMPR1A has also been reported to be a tumor suppressor in skin tumorigenesis." (PMID 23531103, 2013). "We identified no BMPR1A mutations in tumour samples showing LOH on chromosome 10q." (PMID 15026806, 2004). "HPV+ tumour cells displayed 25 extra cell-cell interactions when compared to HPV- cells, and of these BMPR1A showed the most promise as a favorable gene for the prognosis of HPV+ HNSCC patients." (PMID 36420261, 2022).
tumor (continued). "Numerous studies have shown that BMP signalling is maintained in certain tumours such as breast, lung and HNSCC, where tumours overexpress BMP ligands and upregulate the BMP receptors (e.g., BMPR1A)." (PMID 32708289, 2020). "Several reports using genetically modified mouse models highlight the importance of TGFB superfamily signaling components, such as INHA, SMAD3, SMAD1/5, and BMPR1A/BMPR1B, in sex cord-stromal tumor development." (PMID 29221447, 2017). "RHOA, SMAD2, SMAD4, SMAD5, SMAD6, BMPR1A, SMAD7 and MYC-, which thereby emerge as candidate genes to play an important role in CRC tumor metastasis." (PMID 27662660, 2016). "Since previous studies using GBM-TICs have shown tumor-to-tumor variation in the expression of BMP receptors, we first determined the mRNA levels of BMP7, BMPR1A, BMPR1B and BMPR2 genes by real-time qRT-PCR in our primary cell lines." (PMID 25860932, 2015). "That BMP signaling can drive tumor progression has been the impetus behind the use of pharmacologic small inhibitors to the type I BMP receptors, such as BMPR1a, to inhibit BMP signaling." (PMID 26274893, 2015). "We combined mice expressing the MMTV.PyMT oncogene with mice having conditional knockout (cKO) of BMP receptor type 1a (BMPR1a) using whey acidic protein (WAP)-Cre and found this deletion resulted in delayed tumor onset and significantly extended survival." (PMID 26274893, 2015). "This 19-centimorgan minimal region corresponds to the cytogenetic location 10q23–q24 and includes the two tumour-suppressor genes PTEN and BMPR1A." (PMID 15026806, 2004). "Future work should include experimental interrogation of SMAD4, BMPR1A, and other TGF-β pathway alterations in preclinical models, as well as advanced approaches such as single-cell sequencing and spatial biology to dissect tumor–microenvironment interactions." (PMID 41009631, 2025). "Integration of all these data unveiled that the BMP-responsive (i.e. High PROGENy TGF-β/BMP score) pool of tumor cells correlates significantly with BMP receptors expression, in particular to BMPR2, BMPR1B, BMPR1A, and ACVR1 levels, respectively in 8, 5, 5, and 4 out of 10 samples." (PMID 39373720, 2024). "Consistently, the data of RT-qPCR and Western blot conducted in tumor nodules from subcutaneous xenotransplanted tumor models revealed that miR-22-3p was negatively regulated by GBAP1, while both mRNA and protein expression of BMPR1A were positively regulated by GBAP1." (PMID 37658413, 2023). "In many tumor tissues, BMPR1A showed higher expression than nontumor tissues and was closely related to tumor growth and metastasis." (PMID 37416767, 2023). "The probability of interaction between tumor cells and fibroblast receptor-ligand pairs was higher than that of thyroid cells, especially in TGFB1/ACVR1/TGFBR1, FGF18/FGFR1, BTC/EGFR, BMP8A/BMPR1A/BMPR2, and BMP8A/BMPR1A/BMPR2." (PMID 37733241, 2023). "Consistent with the observed increase in WNT related genes in tumor cells, we saw high scores for WNT-related interactions (ligands Sfrp1 and Wnt5a and receptors Fzd6, Fzd7 and Lrp6) and significant BMP-related interactions (e.g. from Bmp4 with Bmpr1a)." (PMID 35600339, 2022). "We first sought to examine the expression levels of BMPR2, BMPR1A and BMPR1B in NB tumour samples." (PMID 32714600, 2020). "BMPR1A expression was globally reduced across all CRC subtypes, but BMPRII expression was retained and BMPR1B expression was upregulated specifically in mesenchymal tumours." (PMID 28299802, 2017). "However, this is not truly consistent with our finding that lower levels of BMPR1A occur in primary tumour with bone metastasis group compared to primary tumour without distant metastasis in the E-MTAB-4003 cohort." (PMID 37333824, 2023).
cancer (42 papers, 2010 to 2025). A tumor composed of atypical neoplastic, often pleomorphic cells that invade other tissues. "The identification of the BMPR1A pathogenic variant in our patient leads to increased cancer screening recommendations for both our patient and potentially his relatives." (PMID 41250769, 2025). "Yet even after this discovery, it was clear that these polyps were unlike many of the aggressive adenomatous intestinal polyps caused by WNT activation, and it was observed that BMPR1a polyps would only rarely progress to carcinoma." (PMID 26274893, 2015). "The patient was informed his lifetime risk of developing cancer may be lower than someone who is heterozygous for a BMPR1A pathogenic variant; however, the percent mosaicism in other tissues (i.e., colorectum and stomach) is unknown." (PMID 41250769, 2025). "SMAD9 and ENPP6 are both involved in bone mineralization and could be involved in cancer like the gene BMPR1A (bone mineralization protein 1A), where variants predispose to CRC." (PMID 39543761, 2024). "A total of 75 index cases with CPs and a personal/family history of cancer were analyzed to identify genetic alterations in major hereditary polyposis-associated genes (APC, BMPR1A, MUTYH, PTEN, SMAD4, STK11)." (PMID 39518056, 2024). "In family 17, a VUS was found in the BMPR1A gene (c.440T>C, p.Phe147Ser) in a 68-year-old male patient with a personal and family history of cancer." (PMID 39518056, 2024). "The patient had a family history of cancer, and all affected living relatives were screened for the BMPR1A VUS." (PMID 39518056, 2024). "In a study by Aytac and colleagues, following regular surveillance and appropriate polypectomies, 4/27 individuals with SMAD4 DCVs developed cancer, in comparison to 0/8 of BMPR1A + JPS patients." (PMID 38066625, 2023). "One proposal suggests that BMPR1A is a so-called “landscaper”, which means that a damaged version of this gene creates a microenvironment that promotes the survival of cancer cells." (PMID 36553592, 2022). "Specifically, from dbMTS, we identified 23 candidate genes, two of which (BMPR1A and XIAP) were associated with diseases that increased the risk of cancer in patients." (PMID 32824926, 2020). "Six pathogenic variants (in BRCA1,BMPR1A,FANCA,FANCC,NBN genes) with cancer related phenotype and three unsolicited variants (in BRCA2,PALB2,RAD50 genes) were reported to patients." (PMID 31937788, 2020). "BMPs exert their biological effects through bone morphogenetic protein receptor type 1A (BMPR1A), also known as ALK3, which is a transmembrane serine/threonine kinase expressed in several tissues and cancers." (PMID 23531103, 2013). "Furthermore, looking at intersections between both cancer types we found BMPR1A, WDTC1 (WD and tetratricopeptode repeats 1) and EHD3 (EH-domain containing 3) mutated in both tumors." (PMID 21203531, 2010). "BMPs, cytokines that control the function of many types of cells, exert their role through BMPR1A, BMPR1B, and BMPR2 class receptors with many other receptors in each class, and loss of function can be associated with muscular-skeletal and, cardiovascular diseases, cancer, or CP." (PMID 37238140, 2023). "In addition, we identified three heterozygous candidate missense variants in known cancer susceptibility genes (BMPR1A,BRIP1, and SRC), three truncating variants in possibly novel cancer genes (CLSPN,SEC24B, SSH2) and four candidate missense variants in ACACA, NR2C2, INPP4A, and DIDO1." (PMID 30809968, 2019). "Had we followed typical guidelines for genetic testing, testing may not have been offered to this patient, and the BMPR1A pathogenic variant may not have been identified until additional polyps and/or cancer were later identified in the patient and/or his offspring." (PMID 41250769, 2025). "In another study by Blatter and colleagues, incidence of cancer was also higher in SMAD4 carriers, with 20.5% of patients with GI cancer (26/127), compared to 8.4% (8/94) in BMPR1A carriers (p = 0.015)." (PMID 38066625, 2023).
cancer (continued). "In conclusion, these data demonstrated that the activation of LAPTM5 in lung metastases is a common molecular event shared by several types of human cancer, and that the LAPTM5/WWP2-based lysosomal regulatory pathway mediates the ubiquitination and degradation of BMPR1A." (PMID 35842443, 2022). "CUVs from the genes MYO1E, SARDH and ISLR appeared in two distinct individuals with cancer from this non-Caucasian cohort, while CUVs from PCDHB16 and known CPG BMPR1A appeared in a single individual with cancer." (PMID 32778766, 2020). "Some mutations in several cancer-related genes such as BMPR1a are also detected in FCCX, but an independent cohort of 22 probands from FCCX families have revealed that BMPR1a mutations are not a major contributor of FCCX incidence." (PMID 29849630, 2018). "Nonetheless, given current data, no UGI surveillance for BMPR1A carriers could be justified due to lack of UGI pathology reported, especially cancer." (PMID 38066625, 2023). "In addition, downregulation of the BMP receptors BMPR1A, BMPR1B, and BMPPR2 in COL1-PC3SFRP2 suggests that the secreted BMPs might be not utilized by the cancer cells in an autocrine manner." (PMID 36552843, 2022).
infection (6 papers, 2012 to 2025). The state of being infected such as from the introduction of a foreign agent such as serum, vaccine, antigenic substance or organism. "Four days post infection, control or Bmpr1a-deficient progenitor cells isolated from white and brown adipose depots were co-cultured with macrophages for 24 h." (PMID 27209464, 2016). "Initially, we evaluated the expression of Bmpr1a mRNA carrying exon 4 deletion after Ad-Cre infection." (PMID 22701178, 2012). "We established that mycobacteria-activated BMP signaling required canonical receptors BMPR2 and BMPR1a, as overexpressed CA BMPR1a spurred an activation of BMP signaling, while a dominant-negative form of BMPR2 failed to activate the cascade even during infection." (PMID 29449840, 2018).
genetic disorder (3 papers, 2012 to 2024). "It is a genetic disorder with an autosomal dominant form of inheritance, and pathological variants in the SMAD4 gene (17%–35%) or the BMPR1A gene (17%–25%) have been established as the cause." (PMID 38191939, 2024).